OTUD7A (OTU deubiquitinase 7A)
Description:
Deubiquitinase, which cleaves 'Lys-11'-linked polyubiquitin chains. Might be required for PA28-20S proteasome assembly (Probable).
Synonyms: C15orf16; CEZANNE2; OTUD7; C16ORF15; NEDHS
Tractability: PROTAC: its protein half-life has been measured.
Gene: Protein-coding gene on chromosome 15 (31,475,398 to 31,870,789, reverse strand). Ensembl gene ENSG00000169918.
Subcellular location: Cytoplasm; Nucleus
Subcellular location (Human Protein Atlas): Cytosol; Nucleoli
Pathways (Reactome):
Metabolism of proteins: Ovarian tumor domain proteases
Gene Ontology:
Molecular function: cysteine-type deubiquitinase activity; protein binding; DNA binding; zinc ion binding
Biological process: protein K11-linked deubiquitination; protein deubiquitination; protein deubiquitination involved in ubiquitin-dependent protein catabolic process
Cellular component: cytoplasm; cytosol; nucleus
Genetic constraint (gnomAD): Loss-of-function variants: 6 observed, 54.9 expected, observed/expected ratio (o/e) 0.11, 90% interval 0.059 to 0.22. The upper end of that interval is the gene's LOEUF score, 0.22, which puts it in group 1 of 6, group 1 being the genes least tolerant of losing a copy. Missense variants: 801 observed, 928.05 expected, observed/expected ratio (o/e) 0.86, 90% interval 0.81 to 0.92. Synonymous variants: 472 observed, 412.71 expected, observed/expected ratio (o/e) 1.14, 90% interval 1.06 to 1.23.
Gene-disease validity (ClinGen):
ClinGen rates the evidence that OTUD7A causes each of these diseases.
complex neurodevelopmental disorder (autosomal recessive): Limited. A disorder that involves more than one phenotype associated with the central nervous system, including but not limited to intellectual disability, autism, and seizures (epilepsy).
Homologues: Orthologues: chimpanzee OTUD7A (99% identical), macaque OTUD7A (99% identical), dog OTUD7A (96% identical), pig OTUD7A (95% identical), rat Otud7a (93% identical), mouse Otud7a (93% identical), rabbit OTUD7A (76% identical), tropical clawed frog otud7a (76% identical), zebrafish otud7a (72% identical), guinea pig OTUD7A (71% identical). Paralogues in human: OTUD7B (54% identical), TNFAIP3 (20% identical).
Diseases named in the same sentence as OTUD7A in open-access papers:
OTUD7A is named in the same sentence as 34 diseases in open-access papers, as found by Europe PMC text mining. Sharing a sentence is not in itself a finding about the gene and the disease. The quoted sentences say what the papers report.
epilepsy (4 papers, 2016 to 2023). A brain disorder characterized by episodes of abnormally increased neuronal discharge resulting in transient episodes of sensory or motor neurological dysfunction, or psychic dysfunction. "Case reports revealed that homozygous loss of function mutations in OTUD7A are associated with severe epilepsy, dystonia and ID." (PMID 36604605, 2023). "Recent studies have shown that out of the six protein-coding genes that are typically encompassed in the deletions, OTUD7A is the most likely candidate to cause associated epilepsy." (PMID 33335288, 2021). "In 2021, another patient with epilepsy and developmental delay, as well as severe hypotonia, was reported to have a OTUD7A mutation, a homozygous de novo frameshift E375Dfs*11, in addition to a 15q13.3 microdeletion spanning part of OTUD7A." (PMID 35327449, 2022). "The OTUD7A protein–protein interaction network included synaptic, axonal, and cytoskeletal proteins and was enriched for ASD and epilepsy risk genes (Ank3, Ank2, SPTAN1, SPTBN1)." (PMID 36604605, 2023). "Further support for the involvement of OTUD7A in epilepsy came when a patient with epileptic encephalopathy and severe developmental delay was found to have a homozygous missense mutation in OTUD7A, L233F." (PMID 35327449, 2022).
Ewing sarcoma (4 papers, 2021 to 2025). A small round cell tumor that lacks morphologic, immunohistochemical, and electron microscopic evidence of neuroectodermal differentiation. "Speckled POZ protein (SPOP) and OTU structural domain-containing protein 7A (OTUD7A) control the turnover of EWS-FLI1 protein in Ewing sarcoma." (PMID 39816677, 2025). "In conclusion, targeting the SPOP/OTUD7A-EWS-FLI1 axis offers a promising therapeutic strategy for Ewing sarcoma, particularly in cases driven by the EWS-FLI1 fusion protein." (PMID 40521202, 2025). "Evaluation of transcriptomic data for Ewing sarcoma cell lines and Ewing sarcoma tumors also revealed levels of OTUD7A mRNA expression." (PMID 34060252, 2021). "Using artificial‐intelligence (AI)‐aided virtual drug screening, we identify the first OTUD7A catalytic inhibitor, which limits Ewing sarcoma growth in vitro and in mice by degrading EWS–FLI1." (PMID 34060252, 2021). "Remarkably, induced depletion of OTUD7A led to reduced EWS–FLI1 protein levels in multiple Ewing sarcoma cells, including A673, MHH‐ES‐1, and EWS894." (PMID 34060252, 2021). "In our study, we find that both genetic and pharmacological inactivation of OTUD7A impede not only Ewing sarcoma growth but also decreased motility." (PMID 34060252, 2021). "To further understand the pathophysiological function of OTUD7A in Ewing sarcoma, we performed a quantitative proteomics study following genetic OTUD7A inactivation in A673 cells." (PMID 34060252, 2021). "Since, genetic inactivation of OTUD7A reduced Ewing sarcoma proliferation and motility, sought to target OTUD7A." (PMID 34060252, 2021). "7Ai, a putative OTUD7A catalytic inhibitor identified through virtual compound screening, reduces Ewing sarcoma cell growth and migration." (PMID 34060252, 2021). "In further support of the inactivation of OTUD7A impeding Ewing sarcoma proliferation, depletion of OTUD7A resulted in significantly reduced colony formation in vitro in A673WT but not A6733A cells." (PMID 34060252, 2021). "We next profiled expression of OTUD7A proteins in a panel of commonly used Ewing sarcoma cell lines commonly used in labs and identified that all Ewing sarcoma cells expressed detectable OTUD7A." (PMID 34060252, 2021). "Together, these data support that OTUD7A largely governs Ewing sarcoma growth by maintaining EWS–FLI1 protein stability and support prior studies demonstrating that EWS–FLI1 acts distinctly from FLI1." (PMID 34060252, 2021). "This study supports the therapeutic targeting of OTUD7A as a novel strategy for Ewing sarcoma bearing EWS–FLI1 and related fusions, and may also be applicable to other cancers dependent on aberrant FLI1 expression." (PMID 34060252, 2021). "Importantly, for all Ewing sarcoma cell lines tested, OTUD7A depletion reduced cell proliferation in vitro." (PMID 34060252, 2021). "We next examined the therapeutic potential of inhibiting OTUD7A in treating Ewing sarcoma." (PMID 34060252, 2021). "Whether OTUD7A protein abundance predicts Ewing sarcoma patient survival remains to be determined." (PMID 34060252, 2021). "Thus, it seems that inhibiting OTUD7A suppresses both Ewing sarcoma proliferation and may affect its ability to disseminate." (PMID 34060252, 2021). "Therefore, in addition to Ewing sarcoma, targeted inhibition of OTUD7A may be relevant for other cancers dependent on FLI1 for proliferation, such as leukemia and kidney cancer." (PMID 34060252, 2021). "Previously, we reported OTUD7A as a vulnerability in Ewing sarcoma by deubiquitinating and stabilizing EWS-FLI1; we have successfully utilized the AtomNet model to identify 7Ai as an OTUD7A catalytic inhibitor." (PMID 36672466, 2023). "Depletion of OTUD7A in Ewing sarcoma cell lines reduces EWS–FLI1 protein abundance and impedes Ewing sarcoma growth in vitro and in mice." (PMID 34060252, 2021).
Ewing sarcoma (continued). "Speckle‐type POZ protein (SPOP) and OTU domain‐containing protein 7A (OTUD7A) are identified as the bona fide E3 ligase and deubiquitinase, respectively, that control EWS–FLI1 protein turnover in Ewing sarcoma." (PMID 34060252, 2021). "Notably, due to the lack of a large cohort of patient data in Ewing sarcoma as a rare cancer, analyzing the Cancer Genome Atlas (TCGA) sarcoma dataset revealed that OTUD7A gene was infrequently altered." (PMID 34060252, 2021).
breast carcinoma (3 papers, 2020 to 2022). "Interestingly, high OTUD7A mRNA levels were associated with worse patient survival in thymoma, uterine corpus endometrial carcinoma, and esophageal squamous cell carcinoma patient cohorts, and neared statistical significance for worse breast cancer survival." (PMID 34060252, 2021).
Intellectual disability (3 papers, 2016 to 2025). "Case 2 presented a 418 kb duplication at 15q13.3 involving CHRNA7 and OTUD7A, a variant of uncertain significance correlated with intellectual disability, speech apraxia, and self-injurious behavior." (PMID 40943430, 2025). "Suzuki and colleagues also reported the biallelic loss of function of OTUD7A in a male patient with hypotonia, intellectual disability, and seizures." (PMID 34659328, 2021).
ovarian tumor (3 papers, 2015 to 2023). "The OTUD7A protein is a member of the ovarian tumor (OTU) family of cysteine protease DUBs." (PMID 36604605, 2023).
cervical cancer (2 papers, 2018 to 2021). A primary or metastatic malignant neoplasm involving the cervix. "Although the effects of COPS5 knock-down in SNAIL expression was most predominant amongst the candidates in lung adenocarcinomas, the other four DUBs (JOSD1, OTUB1, OTUD7A, and OTUD7B) could potentially regulate SNAIL expression in other cancer such as cervical cancers." (PMID 29755680, 2018).
schizophrenia (2 papers, 2016 to 2024). A major psychotic disorder characterized by abnormalities in the perception or expression of reality. "Deletion of the 15q13.3 region containing OTUD7A and CHRNA7 is associated with schizophrenia with loss of function of OTUD7A resulting in impaired synapse function and development." (PMID 39387520, 2024).
autism (1 paper, 2018). Persistent deficits in social interaction and communication and interaction as well as a markedly restricted repertoire of activity and interest as well as repetitive patterns of behavior. "Therefore, genetic studies on the relationship of variants in candidate genes such as CHRNA7 and OTUD7A on 15q11-q13 with autism should be performed." (PMID 30108208, 2018).
Epileptic encephalopathy (1 paper, 2023). A condition in which epileptiform abnormalities are believed to contribute to the progressive disturbance in cerebral function. "We also analyzed iNeurons from a proband with epileptic encephalopathy and a homozygous missense variant in OTUD7A [NM_130901.2:c.697C>T, p.(Leu233Phe)] to gain further insight into the importance of OTUD7A." (PMID 36604605, 2023). "To examine clinically relevant OTUD7A protein interactors, we compared the PPI networks of OTUD7A to the OTUD7A N492_K494del (ASD) and OTUD7A L233F (epileptic encephalopathy) mutations, since both mutations do not impact OTUD7A protein levels." (PMID 36604605, 2023).
glioma (1 paper, 2023). A benign or malignant brain and spinal cord tumor that arises from glial cells (astrocytes, oligodendrocytes, ependymal cells). "OTUD7A (Cezanne2) has also recently been reported to contribute to the DNA damage response in double-strand break (DSB) repair and expression of OTUD7A was substantially reduced in gliomas compared to non-tumor brain tissue." (PMID 37892185, 2023).
kidney cancer (1 paper, 2021). Primary or metastatic malignant neoplasm involving the kidney. "In support of this association, Tet‐induced depletion of OTUD7A in kidney cancer (ACHN) and leukemia (Jurkat and CUTLL1) cells reduced levels of endogenous FLI1 accompanied by reduced cell proliferation." (PMID 34060252, 2021).
sarcoma (1 paper, 2021). A usually aggressive malignant neoplasm of the soft tissue or bone. "The deubiquitinase OTUD7A antagonizes SPOP function to stabilize EWS–FLI1, revealing OTUD7A as a new Ewing‐sarcoma‐growth‐dependent gene." (PMID 34060252, 2021).
cancer (4 papers, 2017 to 2023). A tumor composed of atypical neoplastic, often pleomorphic cells that invade other tissues. "As the NF-kB signalling pathway is implicated in several processes associated with tumorigenesis, OTUD7A by inhibiting it may suppress these cellular processes, suggesting that this deubiquitinase may impose a protective effect in cancer progression." (PMID 37308506, 2023). "Expression of OTUD7A was also reported in different cancer types by Human Protein Atlas." (PMID 34060252, 2021).
neurodevelopmental disorder (3 papers, 2021 to 2025). A behavioral and cognitive disorder with onset during the developmental period that involves impaired or aberrant development of intellectual, motor, or social functions. "Among the genes mapped in the duplicated region are CHRNA7 and OTUD7A, which are frequently associated with neurodevelopmental disorders." (PMID 40943430, 2025). "According to (OMIM #612024), the OTUD7A gene is associated with a neurodevelopmental disorder characterized by hypotonia and seizures." (PMID 40943430, 2025).
psychiatric disorder (3 papers, 2021 to 2023). A disorder characterized by behavioral and/or psychological abnormalities, often accompanied by physical symptoms. "Located on chromosome 15, OTUD7A is one of six genes that contribute to the 15q13.3 microdeletion syndrome, which is associated with neurodevelopmental and psychiatric disorders." (PMID 37892185, 2023). "The 15q13.3 microdeletion syndrome is a genetic disorder characterized by a wide spectrum of psychiatric disorders that is caused by the deletion of a region containing 7 genes on chromosome 15 (MTMR10, FAN1, TRPM1, MIR211, KLF13, OTUD7A, and CHRNA7)." (PMID 33785025, 2021). "OTUD7A, encoding a poorly studied K11-specfic OTU DUB, is located in the 15q13.3 locus, which when deleted causes a wide spectrum of neurodevelopmental and psychiatric disorders." (PMID 33335288, 2021).
tumor (2 papers, 2021 to 2023). "Expression of OTUD7A (aka Cezanne2) in CPh was significantly downregulated to 6.8% of normal non-tumor values (F = 81.52, p = 5.34 × 10−12)." (PMID 37892185, 2023). "Moreover, depletion of OTUD7A dramatically reduced tumor growth and tumor formation of A673, but not A6733A cells grown as xenografts." (PMID 34060252, 2021).
OTUD7A also shares sentences with these, for which no sentence is quoted: autism spectrum disorder (2 papers); amyotrophic lateral sclerosis (1); ciliopathy (1); Cognitive impairment (1); developmental delay (1); dyspraxia (1); esophageal squamous cell carcinoma (1); generalized anxiety disorder (1); genetic disorder (1); hepatocellular carcinoma (1); leukemia (1); lung adenocarcinoma (1); microdeletion syndrome (1); osteopetrosis (1); soft tissue sarcoma (1); Speech apraxia (1); thymoma (1); uterine corpus endometrial carcinoma (1).